IDH1 (isocitrate dehydrogenase (NADP(+)) 1)
Diseases named in the same sentence as IDH1 in open-access papers (continued):
Sharing a sentence is not in itself a finding about the gene and the disease.
glioma (continued). "For instance, while IDH1 mutations were more common in low-grade gliomas, they were occasionally observed in high-grade tumors as well, and they were independently associated with prolonged survival in both cohorts." (PMID 30526857, 2018). "Later single-cell studies in glioma focused on lower-grade gliomas and the effects of IDH1 mutational status." (PMID 30041684, 2018). "In this study, we provide more evidence to support the finding that the regulation of PD-L1 also known as cluster of differentiation 274 (CD274) glioma expression is directly associated with tumor IDH1 mutation status." (PMID 29643764, 2018). "Based on this, we directly measured proline and 2HG concentrations in IDH1-mutated gliomas and found that the steady-state levels of these metabolites were significantly correlated." (PMID 29562167, 2018). "As a result, IDH1/2 mutation status is routinely being utilized in the clinic to help predict tumor prognosis and guide management decisions for glioma patients." (PMID 30647847, 2018). "Glioma specific CpG island hypermethylation has been related to favorable survival prognosis and associated very closely to IDH1/2 mutation in WHO grade II/III glioma and secondary glioblastomas." (PMID 29535343, 2018). "The majority of low-grade glioma harbor an IDH1 or 2 mutation, which is associated with a glioma CpG island methylator phenotype (G-CIMP)." (PMID 29368212, 2018). "In this study, we revealed the functional role of G0S2 in glioma and elucidated one explanation for the increased survival in glioma with IDH1 mutation." (PMID 30388142, 2018). "This phenotype was replicated in immortalized primary human astrocytes containing the predominant IDH1 mutation (R132H) found in low-grade gliomas, demonstrating the causal role of this single mutation." (PMID 29922517, 2018). "Ranking of amino acids that substitute in glioma mutated IDH1 subtypes observed in the literature among all 20 standard amino acids." (PMID 29303363, 2018). "The metabolic hallmark of this glioma subtype is the high level of the oncometabolite 2-hydroxyglutarate (2-HG) by the mutant IDH1 enzyme via the NADPH-dependent reduction of α-ketoglutarate." (PMID 30279357, 2018). "The role of IDH1 as prognostic marker is controversial; literature data demonstrated that IDH1 mutations correlated with good prognosis in brain tumors, such as glioma, glioblastoma and anaplastic astrocytoma." (PMID 29871612, 2018). "Glioma-CpG Island methylator phenotype (G-CIMP) tumors belong to a proneural subgroup, are more prevalent in low-grade glioma, display distinct copy number alterations and are tightly associated with IDH1 somatic mutations." (PMID 29439493, 2018). "In 2008, the IDH1/2 mutation was discovered in gliomas and has been associated with improved prognoses in gliomas independent of tumor grade (Grade II-IV) or histologic subtype (astrocytoma, oligodendroglioma, oligoastrocytoma)." (PMID 30647847, 2018). "It has been well-established that IDH1/2 WT gliomas demonstrate worse prognoses compared to gliomas with IDH1/2 mutations." (PMID 30647847, 2018). "The immunological landscape of glioma is influenced by IDH1/2 mutations; indeed, in mutated tumors PD-L1 is significantly diminished supporting the rationale of ICi treatment in IDH1/2wt patients." (PMID 30406030, 2018). "Studying IDH1 mutations in gliomas has been hampered by the difficulty in generating appropriate model systems." (PMID 29953513, 2018). "IDH1 mutation is an early event in glioma development, as suggested by the observation of its presence in lower grade tumors." (PMID 30279357, 2018).
glioma (continued). "We further investigated PYCR1 expression in IDH1 WT and mutated gliomas and confirmed that tumors with high 2HG concentrations (for examples) also demonstrated increased expression of PYCR1." (PMID 29562167, 2018). "Several lines of research however, have shown that IDH1 mutations were early events in the development of gliomas and had a different impact on gliomas." (PMID 30061525, 2018). "Four miRNAs (miR-10b, miR-130b, miR-1304 and miR-302b) were highlighted as a marker for a high or low-risk of poor prognosis associated with the IDH1/2 mutations in lower-grade glioma patients." (PMID 30583549, 2018). "NAD+ deficiency is one of the striking features of IDH1-mutant glioma cells, which are highly vulnerable to NAD+ depletion via TMZ treatment or NAMPT inhibition." (PMID 30723695, 2018). "Since the discovery of mutations in isocitrate dehydrogenase 1 (IDH1) in gliomas and other tumors, significant efforts have been made to gain a deeper understanding of the consequences of this oncogenic mutation." (PMID 29562167, 2018). "The mutation status of the IDH1 gene was shown to correlate with outcomes in patients with gliomas using mostly unpaired patient samples." (PMID 29643764, 2018). "IDH1 mutations are novel glioma diagnostic markers, and pyrosequencing results showed that 58 cases had the IDH1 R132H mutation in our 147 glioma samples." (PMID 29733521, 2018). "Glioma patients with mutations in IDH1 are known to have prolonged survival compared to glioma patients of the same grade with wild-type enzyme." (PMID 29320744, 2018). "We therefore sought to examine IDH1 mutation status (the predominant IDH1 mutation) in response to immune landscaping in primary gliomas using RNA-seq datasets culled from TCGA." (PMID 29643764, 2018). "To exploit this vulnerability, we treated glioma and fibrosarcoma cells that harbor an IDH1 mutation with an inhibitor of nicotinamide adenine dinucleotide (NAD+) salvage pathway, FK866, and observed decreased viability in these cells." (PMID 30597885, 2018). "While the association between the hypermethylator phenotype and IDH1/2 mutation in gliomas has been well-established, the majority of individual genes involved remain to be identified." (PMID 30647847, 2018). "Mutations in isocitrate dehydrogenase 1 (IDH1) are characteristic of low-grade gliomas and secondary upgraded glioblastomas." (PMID 29619216, 2018). "HIF1α importance in glioma is highlighted by the fact that mutations in IDH1/2 can lead to accumulation of HIF1α, however the most recent report states otherwise." (PMID 30510501, 2018). "Low miR-770 expression was associated with an advanced WHO pathological grade of glioma (p < 0.001), IDH1 mutation (p < 0.001) and a high KPS score (p < 0.001)." (PMID 30524203, 2018). "Recurrent heterozygous mutation of isocitrate dehydrogenase 1 gene (IDH1), predominantly resulting in histidine substitution at arginine 132, was first identified in glioma." (PMID 30416682, 2018). "Factors including age at diagnosis, WHO Grade, ADAR3 expression, MGMT promoter methylation, IDH1/2 mutation status and radiotherapy were significantly associated with the OS of glioma patients." (PMID 30524204, 2018). "The IDH1 mutation also induces metabolic reprogramming that often differs from that observed in IDHwt gliomas." (PMID 29619216, 2018). "The IDH1/2 mutations are relatively rare in paediatric gliomas but occur at high frequency in adult lower grade gliomas." (PMID 30087349, 2018). "Aim was to develop a full automatic clustering approach of the time-activity curves (TAC) from dynamic 18F-FET PET and evaluate its association with IDH1 mutation status and survival in patients with gliomas." (PMID 29953478, 2018).
glioma (continued). "IDH1 mutations are more common in low grade gliomas and in secondary GBM and predict longer survival." (PMID 29422017, 2018). "The single nucleotide polymorphism (SNP) rs11554137 (IDH1105GGT) at codon 105 of IDH1 has been reported in patients with several tumor types, including those with glioma." (PMID 29535392, 2018). "IDH1 mutations are actionable in acute myeloid leukemia, cholangiocarcinoma, and glioma (OncoKB level 3)." (PMID 30442178, 2018). "In glial tumors, IDH1/2 mutational status is regarded as one of the most important diagnostic and prognostic biomarkers." (PMID 30211116, 2018). "The TCGA analysis confirmed our previous results that increased TAGLN2 expression was significantly associated with IDH1/2 WT and higher grade gliomas." (PMID 30647847, 2018). "Glioma patients with IDH1 mutations also show better therapeutic responses and longer survival, the reasons for which are yet unclear." (PMID 29439493, 2018). "This suggests that the individual genetic background of each glioma cell line causes larger transcriptomic changes than the IDH1 status or the oxygen levels." (PMID 30257451, 2018). "In a similar manner, NCH612 and BT-142 IDH1-R132H-positive glioma stem-like cells showed a high susceptibility toward ABT263 treatment as reflected by nanomolar IC50-values." (PMID 29057925, 2017). "This mutation is analogous to the most common mutation found in low-grade gliomas and secondary glioblastomas in the human ortholog IDH1." (PMID 28346139, 2017). "It is worth mentioning here that the compiled evidence suggests that in glioma, IDH1 activating mutation is often the first mutation to occur in that tumor." (PMID 28785398, 2017). "A large proportion (i.e., 60-90%) of low-grade gliomas harbor a heterozygous mutation (R132H) in the gene encoding the cytosolic isoform of isocitrate dehydrogenase (IDH1)." (PMID 29050286, 2017). "It was also found that many of the grade II/III gliomas and secondary GBMs that are IDH1 wild type had mutations at IDH2 R172." (PMID 28785398, 2017). "We first determined IDH1R132H mutation in glioma tumor tissue due to it is the most common missense mutation in IDH1 gene." (PMID 28948065, 2017). "PDGFRA amplifications are also described as a bad prognostic marker in adult IDH1 mutated high-grade glioma and adult anaplastic astrocytoma." (PMID 29312620, 2017). "Our data identify remarkable differences in the phospholipid composition of gliomas harboring the IDH1 mutation." (PMID 29054837, 2017). "To accomplish this, we screened peripheral blood EVs from 21 patients (20 diagnosed with low- and high-grade glioma and 1 brain metastasis) for the presence of IDH1 mutations, the most relevant mutation for human glioma diagnostic and prognostic." (PMID 27902458, 2017). "The expressional levels of P2RY12 are significantly higher in gliomas with the IDH1 (R132H) mutation as compared to the IDH wt gliomas." (PMID 28073370, 2017). "It was demonstrated as an independent prognostic indicator, and showed interrelationships with known molecular marks such as MGMT promoter methylation status, and glioma CpG island methylator phenotype (G-CIMP) or IDH1 mutations." (PMID 29163774, 2017). "Mutations in the IDH1 gene (mainly in codon 132) are described in solid tumors as well as in haematologic malignancies such as glioma, acute myeloid leukemia and chondrosarcoma." (PMID 29312620, 2017). "IDH1/2 are found on chromosome 2 and mutations are found in upward of 80% of low grade gliomas, with 93% of those mutations occurring in IDH1." (PMID 29099032, 2017). "Here, we used DLR to determine IDH1 mutation status in a low-grade glioma cohort composed of 151 patients." (PMID 28710497, 2017). "Isocitrate dehydrogenase 1 (IDH1) mutation is common in low-grade glioma (approximately 80%) and acute myeloid leukemia (approximately 10%)." (PMID 28403884, 2017).
glioma (continued). "In glioma patients, mutations in IDH1 typically occur at the arginine residue located at amino acid position 132 resulting in several protein variants." (PMID 29062039, 2017). "Patients with IDH1 gene mutations experience more favorable prognosis than those with wild-type IDH1 gliomas." (PMID 29097933, 2017). "Higher glioma tumor grade was associated with increased mdNLR values, but mdNLR scores were similar among cases whose tumors contained IDH1 vs TERT promoter mutation." (PMID 28184256, 2017). "All the results suggest that IDH1 and non-IDH1 mutated glioma subtypes are caused by mutational disruption of different genes but similar pathways." (PMID 29046615, 2017). "Altogether, 80–90% of adult grade II/III gliomas and secondary GBMs harbor mutations at either R132 of IDH1 or R172 of IDH2." (PMID 28785398, 2017). "In contrast to IDH1-mutant gliomas, ATRX mutations associated with H3G34V, ZMYND11, EP300, or BRAF V600E were stable across the disease course in our study." (PMID 29084603, 2017). "While glioblastomas are histologically and molecularly heterogeneous, when present, the IDH1 (R132H) mutation is seen in virtually all glioma cells throughout the entire tumor." (PMID 29057925, 2017). "The diagnoses of low-grade glioma were re-confirmed independently by 2 pathologists for each case, and the IDH1 mutation statuses were confirmed by Sanger sequencing." (PMID 28710497, 2017). "The ratios of IDH1-mutated to IDH1 wild-type tumors are in agreement with mutation frequencies from earlier reports of TCGA glioma data and other datasets." (PMID 28467784, 2017). "IDH1 mutations are described in 80% of gliomas, 20% of acute myeloid leukemias (AMLs) and in certain cholangiocarcinomas, thyroid cancers and chondrosarcomas." (PMID 28578659, 2017). "Regarding to hemispheric glioma, patient with tumor located in frontal lobe tends to be younger, IDH1 mutation and longer survival time." (PMID 28915860, 2017). "Water suppressed proton-magnetic resonance spectroscopy (1H-MRS) has been explored to noninvasively detect 2-HG in gliomas for identification of IDH-1 gene mutation." (PMID 29097933, 2017). "The discovery of IDH1 mutations in human glioma and the recent clinical findings in IDH1- and IDH2-mutant acute myeloid leukemia patients highlights the potential clinical utility of brain-penetrant IDH1 mutant-selective compounds." (PMID 29062039, 2017). "Mutation in IDH-1 results in remodeling of the glioma methylome, thus resulting in activation of gene expression characteristics of glioma CpG island methylator phenotype- (G-CIMP-) positive low grade tumor." (PMID 28630875, 2017). "Among these, the glioma CpG island methylator phenotype (G-CIMP) tumors show highest methylation status along with distinct genetic mutations such as IDH1/2 mutations." (PMID 28346397, 2017). "This study is to understand the effects of IDH1 R132H mutation in gliomagenesis and to develop new strategies to treat glioma with IDH1 R132H mutation." (PMID 28052098, 2017). "The recent glioma classification is based on the status of mutations of isocitrate dehydrogenase genes 1 and 2 (IDH1/2), 1p/19q co-deletion, ATRX alterations, and TERT promoter mutation status." (PMID 28730141, 2017). "It became extremely relevant to the field of cancer metabolism when isocitrate dehydrogenase 1/2 (IDH1/2) mutations in glioma and acute myeloid leukemia were discovered." (PMID 27752843, 2017). "Increasing evidences have demonstrated that IDH1 mutations are important genetic events, and closely associated with survival benefit in gliomas." (PMID 29190914, 2017).
glioma (continued). "Currently, mutation specific IDH1 immunohistochemistry is the only available true in situ tumor cell marker for gliomas." (PMID 28945795, 2017). "Gliomas are histologically graded as I-IV and 70-90% of grades II-III gliomas and secondary grade IV glioblastomas contain a mutation in one Isocitrate dehydrogenase 1 (IDH1) allele, with R132H being the most common." (PMID 28178660, 2017). "Frequently, in low-grade gliomas, single amino acid substitution mutations for an arginine residue in the active site of IDH1 and IDH2 evoked production of a new metabolite, 2-hydroxyglutarate (2-HG)." (PMID 29257069, 2017). "The high prevalence of IDH1 mutations in glioma highlights the need for brain-penetrant IDH1 mutant-selective inhibitors as an alternative therapeutic option." (PMID 29062039, 2017). "IDH is known to occur in three structural isoforms, namely IDH1, 2 and 3; however, only mutations in IDH1/2 have been identified in human gliomas." (PMID 28629182, 2017). "The performance of DLR for predicting the mutation status of isocitrate dehydrogenase 1 (IDH1) was validated in a dataset of 151 patients with low-grade glioma." (PMID 28710497, 2017). "Most notably, presence of the isocitrate dehydrogenase 1 (IDH1) mutation was shown to be associated with WHO grade II/III gliomas and secondary GBM as well as a significantly longer progression-free and overall survival." (PMID 27300198, 2017). "Certain gliomas often harbor a mutation in the activity center of IDH1 (R132H), which leads to the production of the oncometabolite 2-R-2-hydroxyglutarate (2-HG)." (PMID 29057925, 2017). "In 2008, mutations in isocitrate dehydrogenase 1 and 2 (IDH1/2) were identified in more than 70% of primary gliomas and secondary glioblastomas (GBM)." (PMID 28427200, 2017). "Remarkably, within gliomas, less than 90% of these point mutations occur at a single residue within the active site of the IDH1 isoform, where the Arginine 132 residue is replaced with a histidine (IDH1R132H)." (PMID 28629182, 2017). "Around 80% of low-grade gliomas and 5–10% of glioblastomas have IDH1/2 mutations and display increased methylation in the gene promoters compared with other glioma subtypes." (PMID 28424758, 2017). "Intraoperative subtyping of gliomas is possible using allele specific PCR for key alterations (IDH1, pTERT) but remains restricted to hotspot point mutations." (PMID 28638988, 2017). "Hotspot mutations in isocitrate dehydrogenase 1 (IDH1) initiate low-grade glioma and secondary glioblastoma and induce a neomorphic activity that converts α-ketoglutarate (α-KG) to the oncometabolite D-2-hydroxyglutarate (D-2-HG)." (PMID 28467784, 2017). "We carried out a preliminary classification prediction of IDH1 mutation statuses with T2 flair images of 110 patients with low-grade gliomas." (PMID 28710497, 2017). "The most common mutations identified to date are in the IDH1/IDH2 genes with IDH1 mutations identified in approximately 80% of grade 2/3 gliomas." (PMID 29099032, 2017). "Contrastingly, IDH1 mutation in glioma develops in early phase and is associated with easy detection and good prognosis." (PMID 28403884, 2017). "Of the many molecular changes found in gliomas, mutations in IDH1 or IDH2 occur early during glioma formation, and are associated with better overall survival (OS)." (PMID 28851427, 2017). "Similar to previous studies, IDH1 mutation only tumors were more likely to be seen in astrocytoma with the ratio of 49.3%, while 82.5% triple-positive gliomas belong to oligodendroglioma." (PMID 28915860, 2017). "To better understand the function of the IDH1 R132H mutation, we investigated the effect of this mutation on gene expression in glioma tissues." (PMID 28445981, 2017).